RNY4P34 (RNY4 pseudogene 34)
Gene: Miscellaneous RNA gene on chromosome 2 (200,373,175 to 200,373,269, forward strand). Ensembl gene ENSG00000201649.
Homologues: Orthologues: chimpanzee Y_RNA (99% identical). Paralogues in human: RNY4 (87% identical), Y_RNA (86% identical), RNY4P14 (85% identical), RNY4P3 (85% identical), RNY4P6 (85% identical), RNY4P7 (85% identical), Y_RNA (85% identical), RNY4P10 (84% identical), RNY4P24 (84% identical), RNY4P13 (83% identical), RNY4P18 (83% identical), RNY4P23 (83% identical), and 85 more.